APC (APC regulator of Wnt signaling pathway)
Diseases named in the same sentence as APC in open-access papers (continued):
Sharing a sentence is not in itself a finding about the gene and the disease.
adenoma (continued). "In a previous study, the D1822V variant of the APC gene was found not to be associated with a family history of CRC, but it has the potential to increase the risk of adenoma transformation." (PMID 24959234, 2014). "In the heterozygous APC knockout mouse model (APC-min), neutrophil-derived gelatinase B/MMP-9 stimulates adenoma initiating cell proliferation, promoting adenoma expansion, and implicating gelatinase B/MMP-9 in the expansion of tumour cell populations that lack full APC function." (PMID 24473089, 2014). "Conditional deletion of APC exclusively in the LGR5+ ISCs of a murine model led to the rapid growth and spread of large adenomas in the small intestine and colon, whereas deletion of Apc in the non-stem cell compartment, resulted in the growth inhibition of adenomas." (PMID 24789370, 2014). "In contrast, and remarkably, APC deletion in non-stem TA cell populations failed to sustain significant adenoma growth." (PMID 24920319, 2014). "We aimed to investigate the contribution of methylation of a number of Wnt-regulators other than APC in both nonpolypoid and polypoid adenomas." (PMID 24350795, 2013). "As far as we examined, all the tumors of Tg/APC were adenomas and histologically showed no apparent difference from those of W/APC." (PMID 22876303, 2012). "The APC promoter methylation was exclusively identified in both carcinomas and adenomas from Number 1 and in none of the other members." (PMID 22164339, 2011). "In this study, we analyzed phenotype and genotype data from 82 patients, with multiple (>= 10) synchronous (19/82) or metachronous (63/82) adenomas and negative APC study (except one case)." (PMID 20687945, 2010). "When compared to Polyposis patients without mutations in neither the MUTYH nor the APC gene, MAP patients seemed to develop the lowest number of adenomas, although no statistically significant results have been found." (PMID 19506731, 2008). "In this study direct sequencing was used to identify adenomas and CRC tumors with or without any APC mutations in the MCR region of the gene, and the results were compared to history of smoking." (PMID 16545110, 2006). "Given the relatively low incidence of APC mutations (7.1–37%) in sporadic SBA, in contrast to their high frequency in adenomas, the adenoma–carcinoma sequence may not constitute the predominant pathway in SBA carcinogenesis." (PMID 41008809, 2025). "Specifically, the analysis of individual colonic crypts isolated from adenomas of patients with distinct hereditary polyposis syndromes, as well as from sporadic and Lynch-syndrome derived carcinomas, demonstrated that the ITH for both APC and KRAS alterations was detectable in single crypts." (PMID 33923068, 2021). "Notably, the suppression of APC−/− adenoma growth by hpo heterozygosity was not due to a reduction in JNK (data not shown) or JAK-STAT signaling." (PMID 26853366, 2016). "Notably, although myc is upregulated in Drosophila APC−/− intestinal adenomas and required for their overgrowth, we found that increasing Myc expression in host cells did not rescue their outcompetition or inhibit APC−/− adenoma growth." (PMID 26853366, 2016). "For APC methylation as well as for chromosome 5q loss, no relation was found with the promoter methylation results for SFRP2, WIF-1, DKK3 and SOX17 when combining both adenomas types or in nonpolypoid adenomas or polypoid adenomas, separately." (PMID 24350795, 2013). "However, they did not detect macroscopic adenomas from APC mutant transient amplifying cells located further up the crypt." (PMID 24245614, 2013). "However, in a substantial part of adenomas of both phenotypes no direct APC disruption was observed." (PMID 24350795, 2013).
adenoma (continued). "Alternatively, it might be that truncated APC becomes necessary at later stages of tumoural progression which the animals never reach because the adenomas limit their life span." (PMID 22509309, 2012). "Furthermore, in this study all 16 adenomas analyzed by qRT-PCR displayed augmented APC 1B mRNA levels as compared to normal parathyroid tissues, strongly suggesting that the APC promoter 1B is not epigenetically silenced in these tumours." (PMID 20208994, 2010). "Further analysis revealed that APC mutation status was significantly associated with β-catenin nuclear accumulation and p-YAP expression (P = .054 and P = .05, respectively) and significantly associated with larger tumor size (OR = 8.082, 95% CI = 1.93–33.89) but not with other adenoma features." (PMID 39977302, 2025). "A similar decrease in adenoma count and COX-2 expression was reported when trametinib, a small-molecule mitogen-activated protein kinase kinase (MEK) inhibitor, was administered to APC mutant mice, suggesting that the COX-2 expressing subset could also be maintained by MEK signaling." (PMID 33430285, 2021). "Moreover, some of them, such as APC and RUNX3 were significantly more frequently methylated in patients with UC and cancer compared to patients with non inflammatory adenocarcinoma and CDH13 was more frequently methylated in patients with UC and dysplasia compared to those with adenoma." (PMID 26862732, 2016). "It has been shown that the removal of APC specifically in the intestinal stem cells (ISCs), but not in their progeny, leads to the formation of lesions that progress to adenomas in less than three weeks, suggesting that ISCs may represent the cell of origin of CRC." (PMID 24516653, 2014). "The adenoma often stains positive for PFIB and APC and negative for galectin-3 (GAL-3) and PGP9.5, and its Ki-67 index is often <1%." (PMID 37834940, 2023). "Unlike conventional adenomas, WNT-pathway activation is not due to APC inactivation but is more frequently due to PTPRK-RSPO3 fusions or RNF43 mutations." (PMID 35457279, 2022). "The frequency of APC hypermethylation was similar between CRC and adenoma (data not shown), this result is consistent with previous study." (PMID 28515349, 2017). "The APC/β-catenin pathway was not altered, while MLH1 immunostaining was negative in RCTs and positive in adenomas and normal mucosa." (PMID 23425390, 2013). "ARC influence on COX-2 expression via NF-ƙB might also play a role in FAP adenomas, as both NF-ƙB and COX-2 are shown to be overexpressed in APC negative cases." (PMID 33579312, 2021). "Interestingly, Bmi1 expression was not apparent in adenomas from either group of animals, whereas patches of strong immunoreactivity were found in infiltrating cells from CDX2;APC mice." (PMID 30150766, 2018).
breast cancer (225 papers, 1993 to 2026). A primary or metastatic malignant neoplasm involving the breast. "On the other hand, a somatic nonsense pathogenic variant in BRCA2 (variant allele frequency = 15%) and a two-hit event in APC (VAF = 80%) were also found in her left breast cancer." (PMID 40601170, 2025). "In this study, we investigated the potential association between the APC gene (I1307K variant) and the risk of breast cancer among Jordanian Arab patients." (PMID 40657252, 2025). "The onset and advancement of breast cancer have been linked to aberrant APC/C activity, which affects vital cellular functions like proliferation and genomic integrity." (PMID 38606093, 2024). "For example, dysregulation of APC/C can cause unchecked cell division and genomic instability, which can aid in the development and spread of breast cancer." (PMID 38606093, 2024). "Distribution of VUS in breast cancer predisposing genes were :APC:1(5.8%), ATM:2(11.7%), BRCA1:1(5.8%), BRCA2:5(29.4%), BRIP1:1(5.8%), CDKN2A:1(5.8%), CHEK2:2(11.7%), FANC1:1(5.8%), MET:1(5.8%), STK11:1(5.8%), NF2:1(5.8%)." (PMID 37277882, 2023). "In contrast, most APC mutations that occur in sporadic human breast cancer have been identified outside of the MCR." (PMID 37655825, 2023). "Here, in primary mouse mammary tumor cells, the loss of APC decreased the accumulation of DOX while increasing the protein levels of MDR1 and MRP1." (PMID 37108784, 2023). "The tumor suppressor Adenomatous Polyposis Coli (APC) is altered (gene deletion, promoter methylation, or loss of protein) in up to 70% of sporadic breast cancers." (PMID 37108784, 2023). "Sixteen out of the seventy-six ICD-9 and eighty out of the 186 ICD-10 codes for the APC gene were associated with breast cancer." (PMID 37195695, 2023). "Hypermethylation of the APC promoter can also promote the development of breast cancer, indicating that APC is not limited to association with colorectal neoplasms." (PMID 35303016, 2022). "The APC tumor suppressor gene is inactive in 70% of sporadic breast cancers; APC-deficient tumors resemble the aggressive TNBC subtype." (PMID 36499000, 2022). "We found that the number of missense somatic mutations and mutations in APC (V1125A and R414S) were independent predictors for the overall survival in our breast cancer patients." (PMID 35936696, 2022). "Here, we first reported the identification of a novel APC mutation in Taiwanese breast cancers patients." (PMID 35936696, 2022). "In breast cancer, APC mutation has been associated with overexpression and reactivation of the poor prognosis and tumor metastasis-associated ErbB receptor." (PMID 34540821, 2021). "APC, a DNA repair gene linked to breast cancer has a z-score of -0.3 in breast while a FUGUE score of 0.7." (PMID 34270548, 2021). "It was also shown that inhibitors for the DNA repair kinases ataxia telangiectasia mutated (ATM) and DNA-PK restored doxorubicin-induced apoptosis in doxorubicin-resistant APC-deficient breast cancer cells." (PMID 33105836, 2020). "Seventy percent of patients with sporadic breast cancer lose APC because of mutation or hypermethylation." (PMID 33072328, 2020). "Recently it was reported that APC mutation promoted mammary tumor cell proliferation in a PyMT mouse model through the activation of Src and JNK signaling downstream of FAK." (PMID 33266025, 2020). "Subsequently, the prognostic value of APC (Prob ID: 215310 at) in breast cancer was also performed using Kaplan–Meier plotter; the results confirmed that the lower expression of APC mRNA was associated with the worse RFS of different breast cancer types." (PMID 33363011, 2020). "In breast cancers, the members of the Wnt signaling family are rarely mutated: APC (1.3%), CTNNB1 (0.2%), AXIN1 (0.4%), LRP6 (0.7%), LGR5 (0.6%), TCF7L2 (0.3%), and FBXW7 (1.5%)." (PMID 32210163, 2020).
breast cancer (continued). "In another candidate gene study of normal breast tissue, the same group observed that RASSF1 methylation is associated with breast cancer risk level, and that increasing parity is associated with decreased APC methylation." (PMID 28693600, 2017). "In summary, these results have revealed the molecular mechanisms of APC loss in breast cancer that can guide future treatment plans to counteract chemotherapeutic resistance." (PMID 29262529, 2017). "To interrogate overall survival of breast cancer patients with concurrent APC and APC2 loss, we performed Kaplan–Meier survival analyses in the METABRIC breast cancer cohort." (PMID 27694902, 2017). "Loss of Adenomatous Polyposis Coli (APC) through mutation or hypermethylation occurs in up to 70% of sporadic breast cancer patients." (PMID 29262529, 2017). "Understanding the molecular mechanisms downstream of APC loss in breast cancer will be important in future treatment plans, especially the development of individualized treatment plans." (PMID 29262529, 2017). "Signal transducer and activator of transcription 3 (STAT3) is a potential modulator of chemotherapeutic resistance in the model of APC loss in breast cancer." (PMID 29262529, 2017). "In the stratified analysis by method, significantly increased breast cancer risk was associated with APC methylation by both QMSP method (OR = 3.11, 95% CI = 1.72–5.62, P = 0.0002) and MSP method (OR = 13.38, 95% CI = 4.34–41.25, P < 0.00001)." (PMID 27191268, 2016). "The AUC was 0.81 (95% CI: 0.77–0.84), suggesting detecting APC methylation has a good diagnostic accuracy for breast cancers." (PMID 27191268, 2016). "An increasing number of studies have reported that APC methylation contributes to the predisposition to breast cancer (BC)." (PMID 27478702, 2016). "Methylated APC was shown to be associated with prognostic outcomes in gastric carcinomas, breast cancer, and hepatocellular carcinoma." (PMID 26862903, 2016). "We furthermore simulated the effect of APC inactivating mutations, yielding a stabilization of β-catenin levels comparable to the Wnt-pathway activities observed in colorectal and breast cancer." (PMID 27218469, 2016). "The current evidence suggested that APC promoter methylation was associated with breast cancer risk and clinicopathological characteristics." (PMID 27191268, 2016). "Sulindac and its derivatives are known to decrease beta-catenin expression and beta-catenin transcriptional activities in breast cancer and APC-mutated colorectal tumor cells." (PMID 27281609, 2016). "The Adenomatous Polyposis Coli (APC) tumor suppressor is mutated or hypermethylated in up to 70 % of sporadic breast cancers depending on subtype; however, the effects of APC mutation on tumorigenic properties remain unexplored." (PMID 26049416, 2015). "We observed heterozygous loss of several cancer‐associated genes, including the CTNNA1 (catenin (cadherin‐associated protein), alpha 1) and APC tumor suppressor genes in the breast cancer." (PMID 26432421, 2015). "For example, we found that DNA hypermethylation at APC was positively associated with increased expression among breast cancers (TCGA database)." (PMID 26510686, 2015). "In concordance, mutations in downstream signaling components (e.g. APC and β-catenin) are rarely found in human primary mammary tumors." (PMID 24887235, 2014). "CDC16 encodes a component of the APC complex, which is a cyclin degradation system that governs exit from mitosis and has been with an altered risk of breast cancer." (PMID 25148247, 2014). "The results of the mouse models suggest that APC dysregulation is associated with initiation and progression of at least some breast cancers." (PMID 25406066, 2014). "It is now appreciated that APC mutation is relatively rare in other solid tumors but it is silenced by gene methylation in multiple tumor types, including breast cancer." (PMID 23302090, 2013).
breast cancer (continued). "The diagnostic potential of RASSF1A and APC promoter methylation in cfDNA from breast cancer patients has been investigated in several studies." (PMID 23320751, 2013). "In contrast, in breast cancer cells, which often display elevated Wnt signalling, mutations in APC or β-catenin are rare." (PMID 23144924, 2012). "WNT signaling is frequently activated in colorectal cancers, melanomas, breast cancers, and gliomas due to loss of adenomatous polyposis coli (APC) function and gain of β-catenin activity." (PMID 24213322, 2012). "Mutations in APC that result in constitutive Wnt signalling in breast cancer cells are rare, nevertheless we tested the effect of XAV939 and IWR-1 in DU4475 cells, which harbor an APC mutation." (PMID 23144924, 2012). "In breast cancer, mutations in APC or β-catenin are rare, but elevated levels of β-catenin are prevalent and this aberrant activity is thought to promote mammary carcinogenesis." (PMID 23144924, 2012). "Loss of APC expression and upregulation of β-catenin have been described in human breast cancer and breast cancer cells." (PMID 18841156, 2008). "The expression of APC appeared to be unrelated to the associated levels of APC methylation in breast cancer samples (n=52)." (PMID 18841156, 2008). "Hypermethylation of the APC promoter is also associated with breast cancer, especially lobular breast cancer." (PMID 18485221, 2008). "Somatic APC mutations are reported in only a minority of breast cancers, despite high rates of allelic loss at chromosome locus 5q21." (PMID 18841156, 2008). "Dysregulation of APC/C, however, has been linked to a number of cancers, including breast cancer." (PMID 38606093, 2024). "This suggests that the expression of APC was not the only factor regulating the activity of MRP1, and it was not the main driver of APC-deficient DOX resistance, ultimately supporting the inhibition of MDR1 as a potential therapeutic target in APC-deficient breast cancer." (PMID 37108784, 2023). "Using the innate fluorescence of DOX normalized to each genotype control, we tested whether there was a decrease in the intracellular DOX fluorescence in APC-deficient primary mouse mammary tumor cells." (PMID 37108784, 2023). "APC mutations were associated with a poor prognosis in human breast cancer (log-rank P<0.001)." (PMID 35936696, 2022). "The methylation of key genes related to breast cancer, like retinoic acid receptor beta (RARβ) and adenomatosis polyposis coli tumor suppressor (APC), has been associated with the presence of PAH adducts in breast tumor tissue and various sources of PAH exposure." (PMID 34203568, 2021). "Similarly, inactivating mutations in AXIN and APC genes have also been found to be extremely rare in human breast cancer samples." (PMID 32692756, 2020). "APC is silenced by hypermethylation or mutated in about 70% of human breast cancers." (PMID 33266025, 2020). "This is the first report of this pathogenic APC variant in a case of breast cancer and lung NET." (PMID 31592449, 2019). "Wnt pathway components, including Axin, β-catenin and Adenomatous polyposis coli (APC), are frequently mutated in colorectal adenocarcinoma but this is uncommon in breast cancer samples, where β-catenin activation is not driven by β-catenin gene (CTNNB1) mutations." (PMID 28798698, 2017). "However, there were inconsistent conclusions in the association between APC promoter methylation and breast cancer." (PMID 27191268, 2016). "Therefore, we preformed a meta-analysis to quantitatively assess the association of APC promoter methylation with breast cancer risk and the clinical characteristics observed in breast cancer patients." (PMID 27191268, 2016).